SELENOI (selenoprotein I)
Description:
Ethanolaminephosphotransferase that catalyzes the transfer of phosphoethanolamine (PE) from CDP-ethanolamine to lipid acceptors, the final step in the synthesis of PE via the 'Kennedy' pathway. PE is the second most abundant phospholipid of membranes in mammals and is involved in various membrane-related cellular processes. The enzyme is critical for the synthesis of several PE species and also catalyzes the synthesis of plasmanyl-PE, a lipid required for proper myelination and neurodevelopment, from 1-alkyl-2-acylglycerol.
Synonyms: SelI; EPT1; KIAA1724; SEPI; SPG81
Tractability: Antibody: UniProt predicts a signal peptide or a membrane-spanning region. PROTAC: ubiquitination databases record sites on it.
Target class: Enzyme; Transferase
Gene: Protein-coding gene on chromosome 2 (26,308,547 to 26,395,885, forward strand). Ensembl gene ENSG00000138018.
Subcellular location: Endoplasmic reticulum membrane
Pathways (Reactome):
Metabolism: Synthesis of PE
Gene Ontology:
Molecular function: ethanolaminephosphotransferase activity; phosphotransferase activity, for other substituted phosphate groups
Biological process: phosphatidylethanolamine biosynthetic process; ether lipid biosynthetic process; myelination; lipid biosynthetic process; phospholipid biosynthetic process
Cellular component: endoplasmic reticulum membrane; Golgi apparatus; membrane
Genetic constraint (gnomAD): Loss-of-function variants: 17 observed, 30.64 expected, observed/expected ratio (o/e) 0.55, 90% interval 0.38 to 0.83. The upper end of that interval is the gene's LOEUF score, 0.83, which puts it in group 3 of 6, group 1 being the genes least tolerant of losing a copy. Missense variants: 236 observed, 327.89 expected, observed/expected ratio (o/e) 0.72, 90% interval 0.65 to 0.8. Synonymous variants: 113 observed, 128.89 expected, observed/expected ratio (o/e) 0.88, 90% interval 0.75 to 1.02.
Homologues: Orthologues: chimpanzee SELENOI (97% identical), pig SELENOI (95% identical), dog SELENOI (93% identical), guinea pig SELENOI (92% identical), mouse Selenoi (91% identical), rabbit SELENOI (90% identical), rat Selenoi (89% identical), tropical clawed frog selenoi (70% identical), zebrafish selenoi (69% identical), Drosophila melanogaster CG33116 (44% identical), Drosophila melanogaster CG7149 (41% identical), Caenorhabditis elegans ept-1 (40% identical). Paralogues in human: CHPT1 (26% identical), CEPT1 (25% identical).
Diseases named in the same sentence as SELENOI in open-access papers:
SELENOI is named in the same sentence as 34 diseases in open-access papers, as found by Europe PMC text mining. Sharing a sentence is not in itself a finding about the gene and the disease. The quoted sentences say what the papers report.
hereditary spastic paraplegia (9 papers, 2017 to 2025). Hereditary spastic paraplegias (HSP) comprise a genetically and clinically heterogeneous group of neurodegenerative disorders characterized by progressive spasticity and hyperreflexia of the lower limbs. "SELENOI is important in motor neuron development and function, as demonstrated in hereditary spastic paraplegia, a neurological disorder in which SELENOI is mutated." (PMID 41002422, 2025). "While SELENOI is indispensable for murine embryonic development, rare loss-of-function mutations in humans lead to a form of hereditary spastic paraplegia (HSP) characterized by motor impairment, microcephaly, and hypomyelination." (PMID 38582453, 2024). "Herein, we developed a mouse model of nervous system-restricted SELENOI deficiency that circumvents embryonic lethality caused by constitutive deletion and recapitulates phenotypic features of hereditary spastic paraplegia." (PMID 38582453, 2024). "Deletion of SELENOI in mice prevents embryo development, while loss-of-function mutations of SELENOI in humans lead to hereditary spastic paraplegia." (PMID 37373256, 2023). "Mutations in the human SELENOI gene, found in rare cases, lead to a form of hereditary spastic paraplegia (HSP)." (PMID 37958974, 2023). "Selenoprotein I (SELENOI) is a crucial mediator implicated in human hereditary spastic paraplegia." (PMID 39669976, 2024). "Clues to understanding the contribution of SELENOI dysregulation in ALS pathogenesis come from studies carried out in a group of neurological disorders called hereditary spastic paraplegia (HSP)." (PMID 41002422, 2025).
breast carcinoma (2 papers, 2020 to 2022). "Overall, considering both the CCLE and LINCS datasets, eight selenoproteins were overexpressed (DIO2, GPX1, GPX4, SELENOI, SELENON, SELENOS, TXNRD1 and TXNRD3) and five were down-expressed (DIO1, GPX2, GPX3, SELENOP and SELENOW) in TNBC compared to all other “non-TNBC” breast cancer subtypes." (PMID 35158912, 2022).
prostate carcinoma (2 papers, 2008 to 2020). A carcinoma that arises from epithelial cells of the prostate gland. "We also observed higher levels of DIO1, DIO2, and SELENOS, and lower levels of SELENOI in all the prostate cancer cell lines." (PMID 32933107, 2020).
colitis (1 paper, 2024). Inflammation of the colon. "Taken together, these findings strongly support the notion that SELENOI functions as a novel suppressor of ferroptosis during colitis and colon tumorigenesis." (PMID 38757622, 2024).
colorectal cancer (1 paper, 2024). A primary or metastatic malignant neoplasm that affects the colon or rectum. "Consistently, SELENOI was significantly upregulated in human colorectal cancer tissues, while PLA2G2A, PLA2G5, and ALOX15 were significantly downregulated." (PMID 38757622, 2024).
enteritis (1 paper, 2024). Inflammation of the small intestine. "In addition to the use of antibiotics and NSAIDs for the treatment of enteritis, some trace elements such as selenium and its protein SELENOI have been shown to be effective in reducing intestinal inflammation." (PMID 39767078, 2024).
rectal adenocarcinomas (1 paper, 2024). "TCGA and GEO datasets analysis showed that SELENOI was significantly upregulated in gastric, colonic, and rectal adenocarcinomas." (PMID 38757622, 2024).
serous carcinomas (1 paper, 2024). "The highest SELENOI mRNA levels were observed in high‐grade serous carcinomas, the most common histotype of OV." (PMID 39669976, 2024).
tumor (6 papers, 2021 to 2025). "Tumor xenograft assays also showed that SELENOI deficiency significantly inhibited tumor growth." (PMID 38757622, 2024). "For instance, SELENOI was mostly upregulated in tumor tissues, whereas GPX3 downregulated; the selenoprotein family tended to be downregulated in CHOL but upregulated in UCEC." (PMID 39919065, 2025). "Considering that SELENOI knockdown attenuates malignant phenotypes and promotes cell cycle arrest, these findings suggest a critical role of SELENOI in tumor progression and prognosis prediction." (PMID 39669976, 2024). "In conclusion, our study demonstrated the ubiquitous upregulation of SELENOI in human malignancies and its role in ferroptosis, tumor immunity, and chemotherapy resistance." (PMID 39669976, 2024). "Upregulated SELENOI transcript and protein levels were also confirmed in tumor tissues from our OV cohort and cancer cell lines." (PMID 39669976, 2024). "Recent research has identified key enzymes involved in CD4+ T cell differentiation and the Kennedy pathway—ETNK1, PCYT2, and SELENOI—suggesting a potential correlation between SELENOI and tumor immunity." (PMID 39669976, 2024). "Elevated SELENOI expression correlates with increased tumor malignancy, advanced stages and poorer prognosis, potentially impacting the response to immunotherapy." (PMID 39669976, 2024). "Consistent with in vitro findings, SELENOI knockdown significantly reduced tumor growth in vivo, and this effect was further enhanced by cisplatin treatment in the TUOS3–shSELENOI group (p < 0.05), with no observed adverse effects on mouse behavior, body weight, or organ pathology." (PMID 39669976, 2024). "Since SELENOI is highly expressed in OV, inhibiting its function may offer a new approach to suppress tumor progression and improve OV chemosensitivity." (PMID 39669976, 2024). "Ethanolamine phospholipid synthesis has emerged as an important process for metabolic reprogramming that occurs in pluripotent stem cells and proliferating tumor cells, and this review discusses roles for upregulation of SELENOI during T cell activation, proliferation, and differentiation." (PMID 34681834, 2021).
cancer (2 papers, 2023 to 2024). A tumor composed of atypical neoplastic, often pleomorphic cells that invade other tissues. "Knockdown of SELENOI caused G0/G1‐phase cell cycle arrest and diminished aggressive cancer phenotypes in OV cells." (PMID 39669976, 2024). "While SELENOI mutations are rare in tumors according to the TCGA database, its role in phospholipid synthesis, and plasma membrane integrity, highlights its potential importance in cancer biology." (PMID 39669976, 2024). "However, further studies are needed to elucidate SELENOI's antitumor functions, and its underlying mechanisms, as well as potential side effects of targeting SELENOI to fully understand its impact in OV and other cancers." (PMID 39669976, 2024). "Given the limited understanding of SELENOI's role in cancer, we assessed its expression in human malignancies using the Cancer Genome Atlas (TCGA) and the Genotype‐Tissue Expression (GTEx) databases." (PMID 39669976, 2024). "Consistently, SELENOI protein expression was elevated across various cancers, particularly in female tumors (BRCA, OV, and UCEC)." (PMID 39669976, 2024). "Hyperactive PI3K/Akt signaling confers resistance to oxidative stress and ferroptosis in cancer cells, Interestingly, SELENOI knockdown reduced phosphorylated Akt (p‐Akt) levels at ser473 without affecting total Akt in TUOS3 and OVISE cells." (PMID 39669976, 2024). "In this study, we identified SELENOI as a key regulator of ferroptosis, demonstrating its upregulation in multiple human cancers." (PMID 39669976, 2024). "SELENOI expression was significantly elevated in nearly all cancers." (PMID 39669976, 2024). "Additionally, SELENOI expression was positively correlated with CD4+ T cells and negatively correlated with macrophages in most cancers (p < 0.05)." (PMID 39669976, 2024). "Previous studies have not demonstrated SELENOI's role in cancer immunity." (PMID 39669976, 2024).
intestinal diseases (2 papers, 2024). "In addition to antibiotic treatment, some trace minerals and their proteins such as selenium and SELENOI have been shown to be effective in alleviating intestinal disorders." (PMID 39408328, 2024).
SELENOI also shares sentences with these, for which no sentence is quoted: Obesity (3 papers); lung carcinoma (2); amyotrophic lateral sclerosis (1); diabetes (1); diaphragmatic disease (1); epilepsy (1); Hepatic steatosis (1); infection (1); Intellectual disability (1); Lipedema (1); lipid metabolism disorders (1); melanoma (1); metabolic syndrome (1); metabolism (1); microcephaly (1); neurological disorders (1); osteoporosis (1); ovarian carcinoma (1); postmenopausal osteoporosis (1); progressive neurodegenerative disorder (1); Spastic paraplegia (1); systemic candidiasis (1); viral infection (1).